INS (insulin)
Diseases named in the same sentence as INS in open-access papers (continued):
Sharing a sentence is not in itself a finding about the gene and the disease.
Insulin resistance (continued). "It is known that high insulin levels lead to development to insulin resistance; thus, the homeostasis model assessment to evaluate insulin resistance (HOMA-IR) was carried out." (PMID 31905880, 2019). "In such cases, weight loss immediately upon completion of a successful intervention parallels improvement of surrogates of insulin resistance (fasting insulin) yet upon weight regain on the later follow up—insulin resistance returns to its baseline level." (PMID 31474943, 2019). "Having confirmed the efficacy of SFA in preventing lipid-induced insulin resistance, we further explored the possible influence of ceramide biosynthesis on the insulin- sensitizing effects of SFA." (PMID 31137828, 2019). "Many studies have reported that insulin sensitizers improve insulin resistance and reduce high androgen levels, subsequently ameliorating ovulation disorders in women with PCOS; in particular, use of metformin has become common." (PMID 31472696, 2019). "They developed glucose intolerance, insulin resistance and dysregulated insulin signaling as seen in human T2D." (PMID 31447783, 2019). "From the diabetological point of view, NAFLD and T2D have become a dangerous disease combination due to an increased insulin demand, aggravated insulin resistance, microvascular complications, and hyperglycemia that is increasingly difficult to control." (PMID 31771244, 2019). "In contrast, when insulin action is impaired (insulin resistance), hyperglycemia occurs when insulin secretion is inadequate to overcome the insulin resistance." (PMID 31776781, 2019). "Insulin resistance in women with PCOS is managed by weight loss, lifestyle interventions (i.e. exercise, diet) and insulin-sensitising medications." (PMID 30992038, 2019). "Solutions of 1% to 1.5% glucose administered in clinical studies suppressed elevations in blood ketone bodies, FFA, and the amino acid 3-MH from skeletal muscle protein, increased insulin, and lowered postoperative insulin resistance." (PMID 31083704, 2019). "Ipra significantly attenuated WD-induced hyperglycemia and insulin resistance with a trend of decrease of serum insulin concentration." (PMID 31234839, 2019). "Newstudies have indicated a possible role for vitamin D in insulin secretion, as wellas insulin resistance." (PMID 31091067, 2019). "Insulin resistance can be assessed by insulin responsiveness, which can be evaluated at the receptor level, and insulin sensitivity, which can be evaluated at the post-receptor level." (PMID 31114678, 2019). "In an opposing conclusion from animal models of type 2 diabetes where brain insulin resistance has been confirmed, insulin therapy acting on the hippocampus was found to be unsuccessful in improving cognition." (PMID 31160730, 2019). "Chronic low-grade inflammation, found in abnormal fat tissue, negatively affects the insulin signal transduction pathway, and promotes insulin resistance." (PMID 31398785, 2019). "They assessed plasmaglucose, insulin, and insulin-resistance, and reported that the parameters ofglucose homeostasis and insulin resistance remained unchanged(p>0.05)." (PMID 31091067, 2019). "None of the genetic variants are genome-wide significant (p < 5 × 10−8) for cardiovascular events, so it is unlikely that they predict insulin or insulin resistance by affecting cardiovascular events." (PMID 31508506, 2019). "To determine how blueberry attenuated HFD-induced insulin resistance, we performed morphometric analysis of the pancreas by immunofluorescence staining for insulin." (PMID 31139236, 2019). "On the other hand, the overexpression of miRNA‐29a impaired the insulin‐induced glucose uptake by indirectly acting on Akt, leading to insulin resistance in 3T3‐L1 adipocytes." (PMID 31389668, 2019). "Second, the dysregulated adipocytokine secretory patterns from adipose tissue leading to a pro-inflammatory state can lead to insulin resistance in insulin-sensitive tissues." (PMID 30778042, 2019).
Insulin resistance (continued). "Type 2 DM is the most frequent form of the disease (over 90% of DM patients), characterized by hyperglycemia due to insulin resistance or inadequate insulin secretion." (PMID 31336965, 2019). "Fasting blood sugar, insulin concentration, and insulin resistance significantly decreased in probiotic group compared with placebo group (-28.32 [-50.23 to -6.41], 0.013; -3.12 [-5.90 to -0.35], 0.028; -32.31 [-55.09 to -9.54], 0.007, respectively)." (PMID 29803203, 2019). "T2DM occurs as a result of insulin resistance and the inability of the pancreas to increase insulin, and is characterized by chronic hyperglycemia, impaired glucose tolerance, altered insulin secretion and insulin resistance." (PMID 31075814, 2019). "It has been shown that pro-inflammatory cytokines act in autocrine and paracrine-dependent manner to perpetuate insulin resistance by interfering with several key steps of the insulin-signaling pathway in peripheral tissues." (PMID 31138952, 2019). "In another investigation, it was also shown that ER stress induced insulin resistance through hindering insulin-stimulated glucose uptake." (PMID 30987118, 2019). "The results demonstrated a considerable reduction in the fasting plasma glucose (FPG), serum insulin level, homeostasis model assessment of insulin resistance (HOMA-IR)." (PMID 32043072, 2019). "The same study describes how intrauterine exposure to hyperglycemia to a greater extent impairs OGTT-derived indexes of insulin resistance compared to indexes of insulin secretion." (PMID 31828161, 2019). "In obese patients with chronic inflammation and insulin resistance, a 2-U/hr insulin infusion lowered the plasma concentrations of sICAM-1 and MCP-1 while maintaining blood glucose at normal levels." (PMID 31052277, 2019). "Regular strength training has been reported to lower insulin resistance and improve insulin sensitivity, thereby improving the cardiometabolic profile of diabetic patients." (PMID 31745461, 2019). "The expression of insulin signalling markers were determined to validate the insulin resistance model adopted in the current study." (PMID 31635074, 2019). "Insulin resistance can lead to structural alterations in thebasal lamina of the insulin-responsive organs." (PMID 30507086, 2019). "The significant clinical changes in glucose metabolism in uremic patients are insulin resistance, impaired insulin secretion, increased glyconeogenesis, decreased insulin and glucagon disintegration." (PMID 30881429, 2019). "FDR had a higher baseline glucose, fasting insulin, and insulin resistance as evaluated by the HOMA-IR index." (PMID 30983877, 2019). "The demographic data of cases and controls showed significant differences for different parameters like glucose, insulin, Homeostatic model assessment‐insulin resistance (HOMA‐IR) and lipid profiles (p < 0.000)." (PMID 31250990, 2019). "On the contrary, obesity decreases AT eosinophil numbers leading to reduced insulin sensitivity while an increase in eosinophils in response to IL-15 overexpression improves obesity-induced insulin resistance." (PMID 31130916, 2019). "Given the lack of placebo, small sample size and female only sample, results from this study are cautiously interpreted as showing some efficacy in reducing insulin and insulin resistance and appears to be well tolerated." (PMID 30918489, 2019). "Studies on how inflammatory markers and hormones affect insulin sensitivity in pregnant women with type 1 diabetes, type 2 diabetes, and severe insulin resistance remain to be performed." (PMID 31828161, 2019). "Insulin resistance is a condition where the body tissues become resistant to insulin, resulting in a marked decrease of glucose metabolism in response to insulin; which is associated with dyslipidemia." (PMID 31212585, 2019).
Insulin resistance (continued). "Muscle mass is the primary tissue contributing to whole-body insulin-mediated glucose disposal, and its decline contributes to insulin resistance, which plays a crucial role in T2DM pathogenesis." (PMID 31013777, 2019). "Insulin resistance with impaired insulin signaling and decreased glucose metabolism is observed in patients with dementia." (PMID 30705766, 2019). "Improvements in insulin resistance and insulin sensitivity are the most important therapeutic parameter in patients with type 2 diabetes." (PMID 30841887, 2019). "Adipose tissue is one of the major targets for insulin and adipose tissue dysfunction usually leads to insulin resistance." (PMID 31126054, 2019). "Leptin also increases insulin sensitivity which helps to prevent abnormally high levels of circulating insulin, and somewhat counteracts the role of GH in inducing insulin-resistance." (PMID 31798399, 2019). "This formulation of insulin-resistant T2D as two interacting pathophysiologic entities suggests that appropriate treatment should target both the insulin resistance and the inadequate insulin secretion." (PMID 31776781, 2019). "Under insulin resistance, an impaired insulin cascade is observed not only in classical insulin target tissues (liver, skeletal muscle, and white adipose tissue) but also in the kidney." (PMID 31313501, 2019). "Decreased insulin sensitivity and increased insulin resistance in women before fertilization, inadequate insulin production after conception, and β-cell functional impairment are all believed to be the risk factors for GDM development." (PMID 30621139, 2019). "Further testifying for hepatic insulin resistance, insulin-induced Akt phosphorylation was compromised in the livers of high-fat fed NRK1 LKO mice." (PMID 31541116, 2019). "Analysis of insulin and glucose homeostasis revealed that serum insulin and homeostatic model assessment of insulin resistance (HOMA2-IR) were significantly decreased in db/db AAV8-Arg2 mice." (PMID 30962478, 2019). "The disruption of the MAMs in the liver promotes insulin resistance suggesting MAM integrity being required for insulin signalling." (PMID 31130874, 2019). "The development of therapeutic compounds able to induce GLUT4 expression/translocation can thus improve insulin sensitivity and reduce insulin resistance." (PMID 31731718, 2019). "A higher level of HbA1c induces insulin secretion and hypoinsulinemia inhibits the process of bone formation, and PINP was directly associated with insulin resistance, indicating that HbA1c affects insulin resistance and insulin sensitivity." (PMID 30866902, 2019). "A single oral administration of 0.5 mg/kg Stevioside for 90 min decreased plasma glucose concentrations and lowered the glucose-insulin index (a measure of insulin resistance) during an intraperitoneal glucose tolerance test in the fructose-rich chow-fed rats." (PMID 31438580, 2019). "In a normal pregnancy with an increase in oxidative stress, insulin resistance increases and insulin secretion was decreased, thus linking it to T2DM in some mothers." (PMID 32043072, 2019). "The results revealed that GA inhibited the activation of the phosphorylation of IRS1ser307 and upregulated the expression of AKTser473 and GSK3β in the PI3K/Akt pathway to improve insulin sensitivity under different insulin resistance conditions." (PMID 30871060, 2019). "Cinnamon also reduces insulin resistance by enhancing phosphatidylinositol 3-kinase activity in the insulin signaling pathway." (PMID 31163689, 2019). "Therefore, it is possible that increased DPPIV activity in GDM pregnancies might also affect the release or the activity of circulating of pro- or anti-inflammatory factors, which have been implicated in the dysregulation of insulin signalling and the establishment of insulin resistance." (PMID 31164969, 2019). "Obesity-related insulin resistance and glucose intolerance have been attributed to defects in the insulin signaling pathway." (PMID 31828157, 2019).
Insulin resistance (continued). "Skeletal muscle is the major site of peripheral insulin resistance of which much of the complexity of this disorder remains undefined, including the role of zinc and zinc transporter Zip7 in insulin signaling and glucose metabolism." (PMID 31266232, 2019). "Accumulating studies have suggested miRNAs are closely related to glycometabolic disorders including GDM by regulating placental immunity, pancreatic β cell functions, insulin sensitivity, and insulin resistance." (PMID 31915414, 2019). "Insulin dysregulation, including hyperinsulinemia and insulin resistance, is a core component of equine metabolic syndrome (EMS), which is associated with the development of the painful equine hoof condition laminitis." (PMID 30808423, 2019). "One study among vitamin D deficient (<50 nmol/L) and insulin resistant women reported a positive effect of 4000 IU cholecalciferol/day over 6 months on insulin resistance and insulin sensitivity." (PMID 31416155, 2019). "Cell-based studies demonstrate that insulin resistance is usually an impairment of insulin signaling through the phosphorylation of IRS on serine and threonine residues." (PMID 30871060, 2019). "In this study, we evaluated the association of LRP5 (rs566442) polymorphism with insulin resistance indexes HOMA-IR, QUICKI, insulin-to-glucose ratio, McAuley, revised McAuley, FIRI, and Bennett’s index." (PMID 30866603, 2019). "The root of glucose intolerance, however, is insulin resistance and metabolic inflexibility, which compromises the shutdown of glucose production in response to a glucose/insulin challenge." (PMID 31541116, 2019). "Pro-inflammatory cytokines such as, tumor necrosis factor-α (TNF-α), reduce the insulin-stimulated tyrosine phosphorylation of the insulin receptor and IRS-1, impairing insulin action and inducing insulin resistance." (PMID 30871083, 2019). "The offspring revealed glucose intolerance, hyperinsulinemia, insulin resistance and defects in insulin secretion ofpancreatic β-cells compared to control mice at the 6 months of postnatal life." (PMID 31217932, 2019). "Due to possible interference from TNF-α with respect to insulin signaling, TNF-α is considered a causative agent in the pathogenesis of obesity-associated insulin resistance and T2DM." (PMID 31073335, 2019). "Accumulating evidence has shown that the brain itself develops insulin resistance due to the impairment in the insulin pathway." (PMID 31178685, 2019). "Normal pregnancy is characterized by a state of insulin resistance defined as an impaired response to insulin." (PMID 31002708, 2019). "Insulin can also activate glycogen synthesis; notably, insulin resistance in patients with type 2 diabetes is characterized by impaired glucose oxidation and glycogen synthesis." (PMID 31461405, 2019). "Increased intracellular lipid accumulation and levels of serum FFA are due to a failure of insulin-mediated suppression of lipolysis, and being important mediators of insulin resistance 45-47." (PMID 31839747, 2019). "During hepatic insulin resistance, the increased lipid accumulation and inflammation impair the ability of insulin to inhibit gluconeogenesis and this leads to an increased glucose output." (PMID 30854003, 2019). "Insulin resistance is a condition in which cells fail to respond to normal levels of insulin that occurs mainly within the liver, muscle, and fat tissues." (PMID 30800211, 2019). "Insulin resistance occurs in almost 20–25% of the human population and is defined as a decreased response of the peripheral tissues to insulin action, and consequently impairment in postprandial nutrient storage mainly in skeletal muscle and in the liver." (PMID 31496996, 2019). "In this study, we showed that HFD mice have significant weight gain, increased blood glucose and insulin levels, impaired glucose tolerance, and increased insulin resistance." (PMID 31133649, 2019).
Insulin resistance (continued). "Impaired INSR endocytosis due to increased viscosity and disrupted lipid orientation of the plasma membrane exerts a direct effect on decreased insulin action and development of insulin resistance." (PMID 31658625, 2019). "For the study of how diosgenin and fenugreek seeds modify insulin sensitivity, we used a rat insulin resistance model induced by high-fat diet." (PMID 31080828, 2019). "Several groups have shown that Chico plays a prominent role in the insulin-signaling pathway in Drosophila with Chico-LOF generating pronounced insulin resistance." (PMID 31427921, 2019). "The insulin concentrations used in this study were extrapolated from plasma insulin concentrations of people with hyperinsulinemia/insulin resistance." (PMID 31949435, 2019). "It is characterized by increased glucose and insulin levels in the blood, insulin resistance, metabolic abnormalities, and chronic inflammation (Sjöholm and Nyström, 2006; Ashcroft and Rorsman, 2012)." (PMID 31275108, 2019). "With wild-type mice on HFD, male and female mice accumulate similar levels of VAT, but male mice display higher fasting blood glucose levels, insulin levels, and insulin resistance." (PMID 31554665, 2019). "The main pathophysiological features of type 2 diabetes are insulin resistance in skeletal muscle, liver and adipose tissue, together with impaired insulin secretion." (PMID 30971952, 2019). "Moreover, the development of insulin resistance, caused by prolonged insulin exposure, may mask insulin effects, as neuronal insensitivity to insulin following long-lasting hyperinsulinemia has been shown to potentiate the death of rat cortical neurons upon glutamate treatment." (PMID 31611766, 2019). "Insulin resistance describes the stage at which a greater than normal amount of insulin is required to obtain a normal physiologic response to glucose homeostasis." (PMID 31492821, 2019). "Insulin resistance is generally defined as a reduced response of target tissues, such as the skeletal muscle, liver, and adipocytes, to insulin." (PMID 31976027, 2019). "An ever-increasing demand for insulin production to overcome progressing insulin resistance becomes harmful to the beta-cells and hyperglycemia and increased free fatty acids, cause oxidative stress." (PMID 30837889, 2019). "The decreased insulin sensitivity of myotubes is in line with the in vivo observation of insulin resistance and with previous studies on other statins." (PMID 31455371, 2019). "Insulin resistance is characterized by a lower than normal glycemic response to insulin, which can lead to chronic hyperglycemia with disorders of the metabolism of carbohydrates, lipids and proteins." (PMID 30660196, 2019). "Insulin resistance, a condition where cellular responses to insulin are unsuitable, is found primarily in insulin-sensitive tissues, liver, muscle and fat." (PMID 30717446, 2019). "As widely reported, insulin resistance in skeletal muscle is tightly connected with the deficit in insulin signaling." (PMID 31736878, 2019). "GLP-1 also corrects insulin resistance by stimulating pancreatic cells to produce insulin and normalizing insulin signaling and mitochondrial function in brain neurons." (PMID 31920905, 2019). "As it is known, adiponectin enhances insulin sensitivity, resistin increases insulin resistance, and leptin has anorexigenic activity." (PMID 30996303, 2019). "Non-clinical studies have shown that azilsartan increases the expression of PPARγ and decreases that of tumor necrosis factor-α (TNF-α), a cytokine that reduces insulin sensitivity; therefore, it is expected to improve insulin resistance in clinical settings." (PMID 30943275, 2019). "Whereas, EDB lipophilic and polar extracts were reported to modulate glucose metabolism or lower insulin secretion contributing to the mitigation of insulin resistance in T2DM rats." (PMID 31398785, 2019).